GLI2 (GLI family zinc finger 2)
Diseases named in the same sentence as GLI2 in open-access papers (continued):
Sharing a sentence is not in itself a finding about the gene and the disease.
cancer (continued). "In vivo models have shown that GLI2 overexpression alone can drive cancer development." (PMID 32544250, 2020). "Brd4, like Gli2, is a target in developmental diseases and cancer, and Brd4 inhibitors may be useful in clinical settings in children." (PMID 31292434, 2019). "Interestingly, Gli1 seems to play a more prominent role in cancer than Gli2 or Gli3, at least based on the number of published studies." (PMID 30754706, 2019). "Thus, GLI inhibitors like GANT61 are advantageous in cancers where SMO contains an activating mutation or GLI activation is SHH ligand-independent and driven by e.g. KRAS mutations or by TGFβ-driven GLI2 expression." (PMID 31661013, 2019). "We have data to show that knocking down GLI1 or GLI2 will sensitize cancer cells to 5-FU treatment." (PMID 28413604, 2017). "Down-regulation of GLI1 or GLI2 sensitized cancer cells to 5-FU treatment." (PMID 28413604, 2017). "The effect of TGF-β on KG-1 cells in the current study differed from a previous study which have reported that TGF-β increases the expression level of Gli2 in various human cell types, including normal fibroblasts and keratinocytes, as well as in various cancer cell lines." (PMID 25009639, 2014). "This as well as the difference in cancer types may explain the discrepancies in GLI2 expression and patient outcomes between our results and previous ones." (PMID 25103784, 2014). "Both GLI1 and GLI2 are oncogenes, constitutively activated in many types of human cancers." (PMID 24962990, 2014). "It is also to be noted that in each cancer scenario, there was another activation link from GLI2 which could up regulate GLI1." (PMID 23935937, 2013). "If Gli1 and Gli2 can have additive effects, the specific expression and function of each one may depend on the tumoral context and in the signaling occurring in cancer cells." (PMID 23667589, 2013). "Since the GLI proteins are transcription factors, we hypothesized that GLI1 and GLI2 transcriptionally regulate hTERT expression in cancer cells." (PMID 24086482, 2013). "In addition, six of the frequently hypermethylated genes, i.e., CCND1, COL4A2, HDAC2, AXIN2, ABL1 and GLI2, are included in the pathways in cancer map from the KEGG database." (PMID 22159500, 2012). "Additionally, GC patients with high GLI1/GLI2 and ABCG2 signatures were associated with a shorter overall survival (OS) and higher cancer relapse, suggesting that higher expressions of these genes predicted a poorer outcome in GC patients who underwent 5-FU and cisplatin-based chemotherapy." (PMID 34638233, 2021). "Thus, other mechanisms must exist to account for increased GLI2 gene expression in cancer cells." (PMID 32544250, 2020). "However, several studies report that GLIs (especially GLI1 and GLI2) can be regulated by the cross talk with other signaling pathways in various types of cancers including melanoma, gastric cancer, colon cancer, multiple myeloma, medulloblastoma, pancreatic cancer, glioblastoma, and osteosarcoma." (PMID 32245491, 2020). "Furthermore, the TGF-β/Smad/Gli2 axis has been suggested to be essential for cancer metastasis." (PMID 31297044, 2019). "Importantly, overexpression of GLI1 and/or GLI2 could be correlated with a poor prognosis for the patients in several cancer entities." (PMID 28418873, 2017). "Importantly, anti-GLI2 therapy or combined anti-GLI2 and anti-survivin therapies might decrease survivin in tumors and markedly improve the treatment of cancer." (PMID 26775700, 2016). "This study reveals a novel role for GLI2 in promoting GIN, a hallmark of human tumors, and identifies potential mechanisms that may provide new opportunities for the design of novel forms of cancer therapeutic strategies." (PMID 24481442, 2014).
cancer (continued). "We observed that although the activation pathways (broken red arrows)from SMO to GLI1 and GLI2 via STK36 protein were blocked by the effect of SMO inhibitor in each cancer scenario, HFU could also activate GLI1 and GLI2 in each cancer scenario (solid green arrows)." (PMID 23935937, 2013). "VLCKD-induced nutritional ketosis promoted changes in the methylation of 18 genes (20 CpGs; 17 hypomethylated, 3 hypermethylated) belonged to cancer-related pathways with MAPK10, CCN1, CTNNA2, LAMC3 and GLI2 being the most representative genes." (PMID 40140215, 2025). "ULK3 has also been implicated in oncogenic pathways including its interaction with GLI2, which regulates anti-apoptotic proteins such as BCL-2, linking autophagy to cell survival in certain cancers." (PMID 40831505, 2025). "ROC1 overexpression leads to the ubiquitin-dependent degradation of SUFU, an inhibitor of Gli2, allowing Gli2 to activate the SHH pathway and promote cancer cell growth." (PMID 40635786, 2025). "As previously reported, GLI2 is a transcription factor, which serves a crucial role in SHH signaling to mediate the development of cancers." (PMID 39881254, 2025). "To explore the impact of the GLI family on cancer, we investigated how the GLI1, GLI2, GLI3, and GLI1/2/3 gene sets affect tumors." (PMID 38498906, 2024). "We have confirmed the correlation between IL-33 and markers like SerpinA1, SerpinA3, and EphB2 for SCC and Gli1, Gli2, FOXO3A for BCC as it highlights the complex interplay of cytokines, protease inhibitors, and receptor signaling in cancer." (PMID 39839625, 2024). "Injury-induced populations were highest for TFs related to cell proliferation, self-renewal, and cancer involving both intrinsic (E2F family, MYC, and ZFX) and extrinsic (HIF1a, EPAS1/HIF2a, NFYB, LEF1, GLI2, VDR, and SMAD1/3/5) pathways." (PMID 38905342, 2024). "GLI family zinc finger 2 (GLI2), a downstream effector of FGF19, is induced by the TGF-B/SMAD pathway and is significant in promoting cancer metastasis." (PMID 39544292, 2024). "There is less support for cyclopamine and its analogs as therapies in cancers with bone metastases such as IBC, wherein GLI2 needs to be inhibited further downstream from the HH receptors." (PMID 33494284, 2021). "Gli2, a downstream molecule of TGF-β signaling involved in driving cancer progression toward metastasis, provides cancer cells with a more aggressive phenotype and metastatic ability." (PMID 33388078, 2021). "On the other side, TF SMAD3 was identified to involve in cancer progression by regulating its target genes BECN1, GLI2, and E4BP4." (PMID 33802957, 2021). "Subsequently, we knocked down GLI2 expression in SGC-7901 transfected with miR-144-3p inhibitor, and the results showed that knockdown of GLI2 offset the cancer-promoting effect of miR-144-3p inhibitor." (PMID 34657624, 2021). "Previous work in mouse models has shown that GLI2 over-expression in the skin leads to the development of basal cell carcinoma (BCC), with sustained or aberrant upregulation of SHH/GLI cascade for cancer growth." (PMID 33494284, 2021). "Hypomethylation of SMO promoter has also been detected in other cancers, including prostate, kidney, glioblastoma, and ovarian cancer cell lines, and a positive correlation was identified between SMO and GLI2 transcript levels." (PMID 34572373, 2021). "Among the differentially expressed genes, we found that several genes related to cancer progression (HMGA2, PLD2, MMP9, GLI1, GLI2, SLUG and MDR1) were expressed at a low level after knocking out APN." (PMID 32457292, 2020). "In the current study, we have developed a qRT-PCR method to accurately determine the expression levels of SMO, PTCH1, GLI1, GLI2, and GLI3 in a panel of cancer cell lines." (PMID 32784501, 2020). "PI3K-AKT activity induced an increase in the expression of GLI1 and GLI2 in renal cell carcinoma and chronic lymphocytic leukemia (CLL), leading to increased cancer cell growth and progression." (PMID 32245491, 2020).
cancer (continued). "Expression levels of the HH pathway genes, the HH signaling receptors PTCH and SMO, and the target transcription factors GLI2 and GLI3, varied significantly among the cancer cell lines." (PMID 32784501, 2020). "In this model, transgenic expression of a constitutively active mutant isoform of GLI2 in keratinocytes activates SHH signaling and induces cancer lesions similar to human BCC." (PMID 31963474, 2020). "Gli1 and Gli2 inhibitor include GANT 61 and Arsenic Trioxide that have shown potent inhibition of Gli1 and Gli2 in many cancer cell lines, one of these is GC cells." (PMID 32430068, 2020). "The quick overview of the Catalogue of Somatic Mutations in Cancer (COSMIC) database shows that there are about 100, 30 and 60 sequence variants that could a priori be considered as pathogenic (nonsense substitutions and frameshift indels) found in GLI1, GLI2 and GLI3, respectively." (PMID 30158435, 2018). "The HH signaling pathway, acting through transcription factors GLI1, GLI2, and GLI3, has been identified as critical for the initiation and progression of a number of cancers." (PMID 30201866, 2018). "Recently, FOXC1 has been shown to activate GLI2 in a SMO independent SHH pathway, which partly explains the aggressiveness of BLBC cell and adds a new role for FOXC1 in cancer cell stemness." (PMID 29487724, 2018). "GLI1 and GLI2 directly bind to the NANOG promoter, with the GLI-Nanog axis promoting stemness and growth in several cancers." (PMID 28245563, 2017). "To determine the molecular mechanisms underlying Gli1-mediated 5-FU resistance in LoVo-R cells, we characterized LoVo-R cells with GLI1-shRNAs or GLI2-shRNAs for cell morphology, EMT and expression of cancer stem cell markers." (PMID 28413604, 2017). "In this study, we revealed that the residual cancer cells following treatment with chemotherapeutic reagent cisplatin have elevated expression of hedgehog target genes GLI1, GLI2 and PTCH1, suggestive of hedgehog signaling activation." (PMID 28404967, 2017). "We investigated a panel of 7 human BCCs, and detected strong nuclear GLI2, YAP and β-catenin expression, concomitant with increased phosphorylation of ROCK-substrate MYPT in cancer keratinocytes of all BCC patients compared to in wildtype skin." (PMID 28820907, 2017). "Failure to terminate HH/GLI signaling, which occurs in cancer, leads to an amplified and persistent increase in GLI1 and GLI2 activity." (PMID 24962990, 2014). "In multiple human cancer cell lines including colon, prostate and brain, suppression of GLI1 and GLI2 expression using GANT61, a small molecule inhibitor resulted in reduced expression of hTERT mRNA, protein and enzyme activity." (PMID 24086482, 2013). "AURA knockdown increased the number of ciliated cancer OSE cells albeit to a small, but significant, extent, and this was accompanied by a lower level of the full-length activator form of the GLI2 protein, involved in Hh signaling." (PMID 23351307, 2012). "The preferential expression of cancer stem cells related marker (CXCR4), regulatory genes (BMI1, GLI1, and GLI2) and microRNAs (miR-214, miR-21, miR-221, miR-222 and miR-155) in holoclones were also highlighted." (PMID 21826251, 2011). "There is likely a signal-induced regulatory mechanism that contributes to the cancer activity of GLI2 that is not part of canonical hedgehog signalling." (PMID 41373535, 2025). "By utilizing different cancer single-cell datasets, we gained an understanding of the expression distribution of GLI1, GLI2, and GLI3 at the single-cell level and found that GLI1, GLI2, and GLI3 were mainly highly expressed in fibroblasts." (PMID 38498906, 2024). "Hence, the combined inhibition of GLI1 and GLI2 using the GANT61 inhibitor and AKT inhibitor Perifosine has been shown to inhibit cancer cell growth and promote apoptosis." (PMID 38498906, 2024).
cancer (continued). "This could explain the observed higher effectiveness of BAS 07019774 in reducing the viability of cancer cell lines expressing both GLI1 and GLI2 (U87MG and SK-MES-1) compared to T98G cells, which primarily express GLI1." (PMID 38999049, 2024). "Given that our studies only uncover CRKL is a critical transcriptional target of Hh‐GLI2 pathway in NSCLC cells, it will be interesting to test whether this transcriptional regulation also exists in other types of cancer." (PMID 34076957, 2021). "In human BCC tumors, GLI1 and GLI2 were shown to be significantly elevated biopsy tissues, and GLI1 and GLI2 transcriptionally upregulated basonuclin and cFlip, respectively, to promote cancer cell survival." (PMID 34572373, 2021). "However, in the present case, neither osteoblast-like cells nor pluripotent stromal cells were observed around the osseous matrix, and the carcinoma cells showed osteonectin, osteocalcin, BMP-2, TGF-β1, and Gli2 expression." (PMID 33388078, 2021). "Additionally, in a pan cancer analysis, a positive correlation between TGF-β-related gene expression and GLI1 and GLI2 expression was observed." (PMID 32245491, 2020). "The modulation of GLI2, an oncogenic transcription factor commonly upregulated in cancer, is in many cases not due to genetic defects, suggesting dysregulation through alternative mechanisms." (PMID 32544250, 2020). "A recent study has shown that the mTORC1 substrate, S6K1, directly regulates hedgehog signalling in cancer cells by interacting with and phosphorylating Gli1, but not Gli2 via a SMO-independent mechanism." (PMID 27039827, 2016). "Genetic alterations, including loss of PTCH function, constitutively active SMO, and amplification of GLI1/GLI2 have been reported to activate downstream Hedgehog signaling independent of ligands in various cancers." (PMID 26936993, 2016). "Moreover, genes in the WNT, SHH, and BMP pathways such as WNT5A, FZD7, and FZD5, SHH, SMO, and GLI2 as well as BMP4 were likewise among the upregulated genes and were included in pathway of cancer gene set." (PMID 26998479, 2015). "How GLI2 is regulated by the ERK and AKT pathways and by HIV-1 Tat may lead to insight into TGF-β1 induction during cancer progression and HIV infection." (PMID 22859956, 2012). "Indeed, we here show that PDGFRα and essential components of the Hh pathway, including SMO, PTCH1 and GLI2, localize to primary cilia of wt OSE cells and that cancer OSE cells display increased basal expression of Hh responsive genes." (PMID 23351307, 2012). "After 72 hours of serum starvation, the level of full-length GLI2 decreased in the OSE cancer cell lines and the level of repressor GLI2 increased, but not to levels comparable to those of wt OSE cells." (PMID 23351307, 2012). "Furthermore, Expression of BMI-1, GLI1, GLI2, GLI3 and a list of cancer related microRNAs were also quantified." (PMID 21826251, 2011). "Cyclopamine administration attenuated Hh signaling in the stroma rather than in the cancer cells as reflected by decreased expression of full length Gli2 protein and Gli1 mRNA specifically in the compartment." (PMID 20098680, 2010). "By interaction with Gli2, CCND1 could promote cancer cell proliferation." (PMID 40478912, 2025). "Although several other TFs, such as nuclear liver X receptor α (LXRα) and signal transducer and activator of transcription 3 (STAT3), have been illuminated as the downstream effectors of Tan, no reports showed the involvement of GLI2 in the anti-cancer property of Tan in human tumors." (PMID 38924029, 2024).
cancer (continued). "Following previous work regarding the canonical activation of the Hedgehog cascade in cancer stemness-associated drug resistance and cellular invasion, we discovered in this study a non-canonical lncRNA MIR31HG dependent GLI2 stimulation and subsequent cancer stemness-related phenotypes." (PMID 37950038, 2024). "Here, using whole-exome, targeted capture and RNA-sequencing, we report recurrent FHL2-GLI2 fusion genes in 65% (17/26) of SSTs and other GLI2 rearrangements in additional 15% (4/26) SSTs, none of which are detected in other types of SCSTs (n = 48) or common cancer types (n = 9,950)." (PMID 31896750, 2020). "The transcriptional regulation of TGF-β1 by GLI2 is a new extension to Sonic Hedgehog (SHH) and TGF-β1 cross-regulation and may provide insight into the detrimental elevation of TGF-β1 leading to pathogenesis in cancer and HIV infection." (PMID 22859956, 2012). "Cancers with this type of activation show high levels of ligands, with no expression of the pathway’s target genes (GLI1, GLI2, and PTCH1), which are only detectable in stromal cells." (PMID 36765685, 2023). "In contrast, sub-confluent, non-starved cultures (0 hour) of both cancer OSE cell lines contained a higher level of full-length and a much lower level of the GLI2 repressor form compared to wt OSE cells." (PMID 23351307, 2012).
infection (12 papers, 2005 to 2024). The state of being infected such as from the introduction of a foreign agent such as serum, vaccine, antigenic substance or organism. "Lentiviral infection was used to stably express wild type Gli2 (WT) and Gli2 variants (SA1, SA2, and SA12) in NIH3T3 cells with endogenous Gli2 knocked down via an shRNA targeting the 3′ UTR of Gli2." (PMID 36271509, 2022). "Together, these findings largely evidenced that RS218 α-hemolysin was the major determinant contributing to the infection-caused Gli2 and ZO-1 decrease in BMECs." (PMID 34281571, 2021). "And the in vitro qPCR and Western blot assay also showed a time-dependent reduction of Gli2 in hBMECs upon the infection." (PMID 34281571, 2021). "In addition, introducing Myc-Gli2 into mKapβ2-shRNA cells by lentiviral infection restored the expression of Hh target genes, suggesting that down-regulation of Hh target genes in Kapβ2-depleted cells is due to diminished Gli activator activity." (PMID 28777795, 2017). "In addition our results show that infection of primary naïve CD4+ T cells (low TGF-β1 expressing cells) with a constitutively active GLI2 lentivirus enhances TGF-β1 transcription." (PMID 22859956, 2012). "In the case of the Gli1, Gli2, Gli3, and Gli3R proteins, localization was determined by infection of primary Tg737Δ2–3β-gal mutant and wild-type limb bud cells with adenoviral vectors that express the full-length Gli proteins or the truncated Gli3R fused to GFP." (PMID 16254602, 2005). "We have also shown CMV-infection of human foreskin fibroblast cells (HFF) up-regulates expression of SHH family proteins including ULK3, Gli2 and Rb12." (PMID 38504123, 2024). "Using infection of human cerebral organoids to assess protein changes, we show CMV infection dysregulates localisation and expression of DYRK pathway (DYRK1A, DYRK1B) and SHH pathway (Shh morphogen, Gli2 transactivator, ULK3 kinase, and Rb tumor suppressor protein) proteins." (PMID 38504123, 2024). "However, infection of Tg737Δ2–3β-gal primary limb bud cells with Gli2-expressing virus failed to induce Ptch1 transcription suggesting that Gli2 function requires the activity of Polaris." (PMID 16254602, 2005). "The IF results also supported that both Gli2 and ZO-1 expression (labeled with Cy3) around the BMECs (labeled with anti-CD31-FITC) were significantly reduced by the RS218-WT and RS218-ΔhlyA-phlyCA infection, while the RS218-ΔhlyA strain did not influence the expression of Gli2 and ZO-1." (PMID 34281571, 2021).
adenocarcinoma (3 papers, 2013 to 2025). A common cancer characterized by the presence of malignant glandular cells. "Upon a specific and important reduction in the mRNA levels of Gli1 that did not affect either Gli2 or Gli3 mRNA levels, cell proliferation and cell viability was decreased in A549 adenocarcinoma cells." (PMID 23667589, 2013).
cardiovascular diseases (1 paper, 2026). "Another gene of interest is GLI2, which is involved in embryonic development, multiple organ development, and cell differentiation and may play a role in cardiovascular diseases by downregulated activity possibly leading to less vascular calcification." (PMID 41246799, 2026).